S100A8 (S100 calcium binding protein A8)
Diseases named in the same sentence as S100A8 in open-access papers (continued):
Sharing a sentence is not in itself a finding about the gene and the disease.
colorectal cancer (continued). "However, the precise function of high S100A8/S100A9 expression in colorectal cancer cells remains unclear." (PMID 38817853, 2024). "However, further studies with larger sample sizes are warranted to substantiate the results of this study and to better understand the functions of the S100A8/A9 positive immune cells observed in the tumor microenvironment of colorectal cancer in tumorigenesis and tumor progression." (PMID 25371673, 2014). "Interestingly, S100A8 and S100A9, whose products form the heterocomplex calprotectin, are strongly up-regulated in our study, in agreement with reports on inflammation-associated cancer and in human colorectal carcinomas." (PMID 20459814, 2010). "Previous studies have shown that CCN1 activates the FAK/MEK/ERK signaling pathway in colorectal cancer by binding to integrin αVβ5 to activate STAT3, a key upstream molecule known to regulate S100A8." (PMID 39659236, 2024). "To better understand the localization of S100A8 and S100A9 in cancer tissues, we conducted immunohistochemical analyses on human colorectal cancer samples." (PMID 38817853, 2024). "These considerations underscore the necessity for future studies to broaden the scope of our findings and facilitate a deeper understanding of the intricate interactions between S100A8, S100A9, and the tumor microenvironment in colorectal cancer." (PMID 38817853, 2024). "Our immunohistochemical analyses further confirmed the significant increase in the cytoplasmic presence of S100A8 and S100A9 in the glandular epithelial cells of colorectal cancer tumors compared to normal tissues." (PMID 38817853, 2024). "Our previous findings indicated a significant increase in both RNA and protein levels of S100A8 and S100A9 in colorectal cancer tissues, suggesting a correlation with the malignancy and prognosis of the lesions." (PMID 38817853, 2024). "Using diverse techniques like ELISA, immunohistochemistry, and biodatabase analysis, we found that S100A8 and S100A9 expression levels were significantly elevated in colorectal cancer patient tumor tissues compared to normal tissues." (PMID 38817853, 2024). "S100A8, a calcium- and zinc-binding protein, is regulated by the TGF-β/USF2 axis and induces epithelial‐mesenchymal in colorectal cancer." (PMID 37564208, 2023). "Treatment of macrophages with LPS and S100A8 facilitated the migration of HCT116 and SW480 colorectal cancer cells in a transwell system in vitro." (PMID 34209679, 2021). "Our work demonstrated that S100A8 and S100A9 are linked to the CRC progression, and one of the underlying molecular mechanisms is that extracellular S100A8 and S100A9 proteins contribute to colorectal carcinoma cell survival and migration via Wnt/β-catenin pathway." (PMID 23637971, 2013). "Then the influence of S100A8 and S100A9 in the viability and migration of human colorectal carcinoma cell lines (HCT116 and SW480) and in Wnt/β-catenin pathway was analyzed." (PMID 23637971, 2013). "Expression of S100A8 and S100A9 in colorectal carcinoma and matching distal normal tissues were measured by reverse transcriptase polymerase chain reaction (RT-PCR), immunohistochemistry and western blot." (PMID 23637971, 2013). "Expression of S100A8 and S100A9 in paired of colorectal carcinoma and matched distal normal tissues." (PMID 23637971, 2013). "Specimens from 267 colorectal cancer cases were analyzed by immunohistochemistry to determine GSDMB expression, CD3+, CD4+, and CD8+ T lymphocytes, CD20+ B lymphocytes, CD68+ macrophages, and S100A8+ immune cells." (PMID 38711020, 2024). "Furthermore, our Western blot analysis revealed heightened expression levels of S100A8 and S100A9 in colorectal cancer cells SW480, SW620, and CT26 when compared to normal colonic epithelial cells NCM460." (PMID 38817853, 2024). "S100A8 has been reported to promote cell migration and invasion and EMT in colorectal cancer." (PMID 34400882, 2021).
colorectal cancer (continued). "For instance, studies have shown that the S100A8/S100A9 complex, which has a broad range of intracellular and extracellular functions, suppresses keratinocyte proliferation, but promote the growth and metastasis of colorectal cancer cells." (PMID 29872130, 2018). "Culture of human colorectal cancer cells HT29, HCT116 and LOVO in monocytes/macrophage-conditioned media similarly upregulated S100a8 and S100a9 mRNA expression in the cancer cells, indicating that induction of these genes by the conditioned media was not restricted to murine cell lines." (PMID 27086923, 2016). "Furthermore, differential analysis and pathway enrichment studies revealed a strong correlation between the levels of S100A8/S100A9 and inflammatory signaling pathways in these patients, underscoring their essential roles in the advancement and progression of colorectal cancer." (PMID 38817853, 2024). "Furthermore, our data also show that extracellular S100A8 and S100A9 could promote viability and migration of colorectal cancer cell lines HCT116 and SW480 through upregulation of Wnt/β-catenin pathway." (PMID 23637971, 2013).
systemic lupus erythematosus (32 papers, 2011 to 2025). An autoimmune multi-organ disease typically associated with vasculopathy and autoantibody production. "In vitro and in vivo studies demonstrated that S100A8/9 effectively promoted TLR7 pathway activation and that S100A8/9 deficiency reversed the promoting effect of MDSCs on TLR7 pathway activation in lupus." (PMID 38429401, 2024). "Associations between plasma S100A8/A9 and CV risk have also been found to be valid in healthy individuals and in systemic lupus erythematosus (SLE) patients." (PMID 24453429, 2013). "S100A8 significantly enriched 54 pathways, including systemic lupus erythematosus, cell cycle, and allograft rejection." (PMID 40475761, 2025). "S100a8 is highly expressed on the surface of B cells in patients with systemic lupus erythematosus, with its expression decreasing upon disease treatment." (PMID 38650939, 2024). "Mechanistically, S100A8/9, secreted by lupus MDSCs, enhances IFN-γ production by BMDMs, subsequently promoting TLR7-mediated activation of macrophages and DCs." (PMID 38429401, 2024). "We isolated Gr1highCD11b+ and Gr1lowCD11b+ cells from 9 week old male and female NZBWF1 lupus-prone mice and determined levels of S100a4, S100a8, and S100a9 mRNA." (PMID 34220829, 2021). "To explore whether S100A8/9 contributes to the promotion effect of lupus MDSCs through activation of the TLR7 pathway, we first investigated whether S100A8/9 can regulate the TLR7 pathway activation." (PMID 38429401, 2024). "Interestingly, TNF, IL-17, IL-1, and S100A8/S100A9 have been described to form a positive feedback network driving disease activity in murine models of auto-immune arthritis or systemic lupus erythematosus." (PMID 33643287, 2020). "Serum S100A8/A9 levels in patients with systemic lupus erythematosus (SLE) are elevated, which may be closely related to disease activity.." (PMID 32680574, 2020). "As proposed in earlier studies on S100A8/A9 in healthy middle-aged individuals and patients with systemic lupus erythematosus the origin of serum S100A8/A9 could be circulating neutrophils or thrombocytes." (PMID 30865695, 2019). "For example, in systemic lupus erythematosus (SLE), S100A8/9 levels are significantly elevated and correlate with disease activity." (PMID 40735470, 2025). "In systemic lupus erythematosus (SLE) patients, the serum levels of S100A8/A9 released from polymorphonuclear (PMN) cells are elevated and are particularly increased in patients with anti-dsDNA antibodies and glomerulonephritis." (PMID 29942307, 2018). "Clinical data suggest that, compared with those in patients with inactive SLE and healthy individuals, the expression of S100A8 and S100A9 in patients with active SLE is significantly elevated and positively correlated with systemic lupus erythematosus disease activity index (SLEDAI) scores." (PMID 38429401, 2024). "Taken together, these findings suggest that lupus MDSCs promote TLR7 pathway activation and lupus pathogenesis through the S100A8/9-IFN-γ axis." (PMID 38429401, 2024). "In conclusion, this study demonstrated that lupus MDSCs promote TLR7 pathway activation, contributing to lupus pathogenesis through the S100A8/9-IFN-γ axis." (PMID 38429401, 2024). "Our results indicate that MDSCs may aggravate the pathogenesis of TLR7-mediated lupus by promoting the activation of macrophages and DCs through the S100A8/9-IFN-γ axis, suggesting that MDSC-derived S100A8/9 plays a crucial role in lupus pathogenesis." (PMID 38429401, 2024).
ulcer (30 papers, 2009 to 2025). "Animal experiments have proved that inhibition of S100A8/A9 can repair ulcer progression." (PMID 37450409, 2023). "We found that S100A8 was highly expressed in the IC/BPS ulcer and nonulcer groups (P < 0.01), also in the bladders of EAC mice (p < 0.001)." (PMID 40346703, 2025).
prostate carcinoma (27 papers, 2007 to 2025). A carcinoma that arises from epithelial cells of the prostate gland. "S100A8/A9 are strongly up-regulated in breast, lung, gastric, colorectal, pancreatic, skin cancers and prostate cancer, in inflammation associated with cancer and altered S100A9 expression in carcinomas can lead to chemoresistance." (PMID 25298751, 2014). "By using multidisciplinary analysis of corpora amylacea inclusions in prostate glands of patients diagnosed with prostate cancer we have revealed that their major components are the amyloid forms of S100A8 and S100A9 proteins associated with numerous inflammatory conditions and types of cancer." (PMID 19440546, 2009). "For example, increased expression of S100A8 in prostate cancer models was found to alter the tumor stroma." (PMID 35783639, 2022). "This study was not consistent with previous research showing that hypoxia treatment directly induced S100A8/A9 expression in prostate cancer cells." (PMID 33282877, 2020). "In vitro studies showed that the heterodimer S100A8/A9 is secreted by prostate cancer cells, and extracellular S100A8/A9 activates NF-κB and MAPK signalling." (PMID 32722137, 2020). "For example, phorbol esters stimulate secretion of S100A8/A9 by prostate cancer cells and S100A9 expression is induced in hepatocellular carcinoma through activation of NF-KB signaling." (PMID 25298751, 2014). "Overexpression of the S100A8 protein has been observed in breast, colorectal, gastric, lung, pancreatic, and prostate cancer, wheras underexpression has been shown in various squamous cell carcinomas of the head and neck." (PMID 24885002, 2014). "By using mass-spectrometry, gel electrophoresis and Western blot analyses, the pro-inflammatory S100A8/A9 were found to be a major proteinaceous component of all corpora amylacea specimens obtained as a result of prostatectomy of the prostate cancer patients." (PMID 22489132, 2012). "Additionally, an increase in the expression of S100A8 mediated by hypoxia has been observed in prostate cancer." (PMID 35625760, 2022). "In prostate cancer, S100A8 and S100A9 are upregulated and might be helpful markers in the early stage of prostate tumour progression." (PMID 32722137, 2020). "The role of S100A8 in prostate cancer has been studied with evidence suggesting that it is elevated in prostate cancer and may be involved in MAP kinase and NFK-B signalling." (PMID 17430594, 2007). "This leads us to suspect that S100/calgranulin (particularly S100A8/A9) expression, may have prognostic value in canine prostatic inflammation as has been shown for prostatic cancer in men and could result from exacerbated inflammation through pathways down-stream from S100A8/A9." (PMID 37946179, 2023). "Enhanced secretion of S100A8/A9 in a hypoxic environment may be mediated by hypoxia-induced factor 1 (HIF-1), as HIF-1 was reported to upregulate transcriptional levels of S100A8/A9 in prostate cancer cells by directly activating the S100A8 and S100A9 promoters." (PMID 33282877, 2020). "One of its ligands, S100A8/A9, a heterodimer consisting of S100A8 and S100A9, has been reported to be increased in tissue and serum of prostate cancer patients." (PMID 31806053, 2019). "Recently, S100A8 and S100A9 were identified in amyloid aggregates in corpora amylacea of prostate cancer patients." (PMID 23483999, 2013). "The list of up and downregulated genes in VEGFA165 tumours include known genes involved in neoplasia (e.g. S100A8 involved in leukaemia; S100A9 in prostate carcinoma; BCL9, CCND1 and CTNNB1)." (PMID 22045186, 2011). "In particular, the enhanced secretion of S100A8 and S100A9 was found in human prostate cancer cells." (PMID 19440546, 2009). "Moreover, previous studies demonstrated that PGE2 was necessary for S100A8 expression and found that prostanoid receptor antagonists inhibited the PGE2-mediated increase in S100A8 expression in prostate cancer cells and macrophage." (PMID 27936243, 2016).
prostate carcinoma (continued). "S100A8 and S100A9 expression levels increased in several types of cancer, including gastric, colon, pancreatic, bladder, ovarian, thyroid, breast, skin and prostate cancer." (PMID 25673070, 2015). "Amyloid aggregates of the calcium-binding EF-hand proteins, S100A8 and S100A9, have been found in the corpora amylacea of patients with prostate cancer and may play a role in carcinogenesis." (PMID 23483999, 2013). "S100A8 and S100A9 play critical role in tumor biology and their elevated levels were found in numerous tumors including gastric, colon, pancreatic, bladder, ovarian, thyroid, breast, skin and prostate cancers." (PMID 22489132, 2012). "However, similarly to tissue S100A8/A9+ cell counts, the NLR might be of value for further stratification of the population of dogs with prostatic cancer." (PMID 37946179, 2023).
lung carcinoma (26 papers, 2012 to 2025). "A recent study also demonstrated that stress hormones such as NE and adrenaline cause rapid release of proinflammatory S100A8/A9 proteins by neutrophils, leading to early relapse in lung cancer and ovarian cancer post operation." (PMID 36418844, 2023). "In lung cancers, S100A8/A9 overexpression has been implicated in the promotion of pre-metastatic niches, anchorage-independent invasion, and tumor cell proliferation." (PMID 37256148, 2023). "The expression rates of S100A9 and S100A8 were significantly higher in lung cancer tissues than in para-cancer tissues, and their expression was associated with tumor differentiation degree." (PMID 39516272, 2025). "In an orthotopic lung cancer mouse model, intranasal S100A8 delivery effectively delayed tumor growth and prolonged survival by inducing the antioxidant activity of many key genes and activating immune cells to positively modify the immune microenvironment." (PMID 37701037, 2023). "We previously showed that treatment with anti-S100A8/S100A9 antibodies inhibited metastasis in mouse lung carcinoma (3LL)-bearing mice." (PMID 36932197, 2023). "In lung cancer, S100A8 and S100A9 are expressed in both cancer and stromal cells and high expression has been correlated with positive and negative clinical outcomes." (PMID 35655772, 2022). "S100-A8, thymidine phosphorylase, annexin A2, transglutaminase 2, and annexin A1 were lung cancer individuals’ most renowned over-expressed proteins." (PMID 36552956, 2022). "Here we show for the first time that intranasal delivery of S100A8 delayed lung cancer growth in mice." (PMID 35655772, 2022). "To address this shortcoming, we used an orthotopic syngeneic lung cancer mouse model to investigate the global effects of S100A8 on cancer cells and the lung microenvironment." (PMID 35655772, 2022). "Studies herein showed for the first time that intranasal delivery of S100A8 delayed aggressive lung cancer growth and increased survival in a syngeneic orthotopic lung cancer mouse model." (PMID 35655772, 2022). "Future studies should examine the effects of inhalation of S100A8 on growth of different lung cancer subtypes, or its effect when delivered locally to tumors which rely on an inflammatory and/or redox microenvironment for growth and lung metastasis." (PMID 35655772, 2022). "As S100A8/A9 is considered a key protein in lung cancer metastasis, previously, we developed an anti-S100A8/A9 neutralizing antibody that prevents lung cancer metastasis." (PMID 36354584, 2022). "Taken together, our data support the notion that the newly identified NPTNβ signaling pathway that is initiated by cancer surrounding extracellular S100A8/A9 worsens the disseminating progression of lung cancers." (PMID 32490214, 2020). "In vitro study showed that S100A8/A9 expression results in infiltration of immune cells, especially neutrophils in tumors of the mouse injected with lung cancer cells." (PMID 25298751, 2014). "S10A9 is often co-expressed with S100A8 in lung cancer, forming a heterodimer called calprotectin." (PMID 36674438, 2023). "In addition, studies using a mouse lung cancer model have found that the S100A8/S100A9–EMMPRIN–Vegfa axis promotes tumor angiogenesis and progression, which is associated with the prognosis of lung cancer patients." (PMID 37701037, 2023). "It is therefore plausible that S100A8, by suppressing inflammation, may prevent and/or delay the development of lung cancer." (PMID 35655772, 2022). "Given that most lung cancers develop on a background of chronic inflammation, we hypothesized that the anti-inflammatory properties of S100A8 may limit early-stage growth of lung cancers by favorably modifying the lung immune microenvironment." (PMID 35655772, 2022). "However, mechanisms whereby S100A8 regulates expression of pro-inflammatory cytokines in lungs of mice with lung cancers requires further investigation." (PMID 35655772, 2022).